CCR6 (C-C motif chemokine receptor 6)
Diseases named in the same sentence as CCR6 in open-access papers (continued):
Sharing a sentence is not in itself a finding about the gene and the disease.
infection (continued). "At 48 h after infection, bacterial titers and the number of cerebral bleedings in Ccr6−/− and WT mice were similar." (PMID 24699535, 2014). "In vivo studies on bacterial infections have, so far, been limited to a description of an increase of CCL20 and CCR6-positive cells at the site of infection." (PMID 24699535, 2014). "Ccr6−/− mice developed more severe disease than WT control animals reflected by higher clinical scores 24 h after infection and increased mortality 48 h after infection." (PMID 24699535, 2014). "Culture fluids of infected NP-2/CD4/CCR5 cells on day-seven, NP-2/CD4/CKR-L3 cells on day-42 and NP-2/CD4/CCR6 cells on day-52 were assayed for RT activities when CPE ascended at the level of 80-90% cell infection." (PMID 24980635, 2014). "In contrast, CCR6 showed much weaker coreceptor activity than CKR-L3 taking 10 days more to produce similar levels of infection." (PMID 24980635, 2014). "Similar to circulating NK cells, almost all NK cells in the LN lost CCR6 expression following MPXV infection." (PMID 24147080, 2013). "To investigate long-term consequences of the early hyper-inflammatory response detected in B6.CCR6−/− mice, we investigated the T cell activation state at the peak phase of infection after 4 weeks." (PMID 23028548, 2012). "Six days after infection inflammatory T cells were more frequent in the skin of B6.CCR6−/− than in B6.WT mice indicating a marked activation of those cells in the early phase of infection." (PMID 23028548, 2012). "In B6.CCR6−/− mice increased capability of CD8 cells to produce IFNγ also correlated with higher levels of IL12p40 expression at the peak of infection." (PMID 23028548, 2012). "In this study we provide evidence that Treg cells can be attributed as a major regulatory subtype preventing excessive production of IFNγ and reducing local inflammation after infection in CCR6−/− mice." (PMID 23028548, 2012). "Analysis of the cellular composition at the lesion site after 5 weeks of infection revealed increased numbers of total leukocytes in the footpads of CCR6−/− mice." (PMID 23028548, 2012). "Consistently, higher levels of IL12p40 mRNA in B6.CCR6−/− mice compared to B6.WT mice 4 weeks after infection indicated an over-activation of the Th1/Tc1 immune pathway." (PMID 23028548, 2012). "Among Tc17 cells that were recruited to the lungs of vaccinated mice after infection, the expression of CCR6 (84%) was much higher than that of CXCR3 (49%)." (PMID 22829762, 2012). "The action of HBD-2 was believed to act through the chemokine receptor C-C chemokine receptor 6 (CCR6) to recruit immature dendritic cells (DCs) and memory T cells to the site of infection." (PMID 22570668, 2012). "Although present in low numbers, the frequency of Th17 cells was increased in B6.CCR6−/− compared to B6.WT mice in the early phase of infection." (PMID 23028548, 2012). "The frequency of IFNγ-producing CD8 cells was higher in B6.CCR6−/− compared to B6.WT mice as seen already in the early phase of infection." (PMID 23028548, 2012). "Long-term infection experiments revealed that the absence of CCR6 enhances risk for mortality following M.tb infection, particularly in females." (PMID 42059640, 2026). "This is because CCR6 expression decreased during infant infection." (PMID 39867906, 2024). "However, during infant infection, this difference was lost, and the expressions of CCR6, CCR5, and CXCR3 were found to be equivalent." (PMID 39867906, 2024). "In naive cells, the expression levels of CCR10, CXCR3, and CCR6 were similar during infection." (PMID 39867906, 2024). "As cytotoxic cell migration may play an important role during an intracellular infection such as acute melioidosis, we next assessed the proportion of cells positive for CCR6 amongst T cell populations." (PMID 39008280, 2024).
infection (continued). "CCR6 has a key role in orchestrating the migration of immune cells to inflammatory sites, and this disruption triggers the recruitment of Th17 or Treg cells to the site of infection or injury." (PMID 37092451, 2023). "CCR6 + T cells showed a higher infection rate than their CCR6- counterparts, whether cultured alone or co-cultured with IEC (overall comparisons p < 0.0001)." (PMID 37202790, 2023). "In addition, there seemed to be a preferential depletion of CCR6 + T cells upon infection, as infected T cells in IEC co-cultures have a much lower percentage of CCR6 + T cells." (PMID 37202790, 2023). "The CCR6 chemokine MIP-3α (CCL20) is produced at sites of infection in SIV animal models." (PMID 35055955, 2021). "In contrast, various populations of class-switched MBCs expressing low levels of or no CXCR5 and CCR6, including T-bet+ atypical MBCs, were associated with reduced risk of infection." (PMID 34128836, 2021). "CCR6 is a marker used to identify Th17 cells, which are overrepresented in the GALT, and are among the major cellular targets for HIV being highly susceptible to infection." (PMID 32841266, 2020). "Thus, consistent with superior expression of PPARy inCCR6+ Th17/Th1Th17-polarized versus CCR6-Th1-polarized T cells, T0070907 acted onCCR6+ T cells to upregu-late IL-17A production and limit HIVde novo infection by mechanisms including CCR5down-regulation." (PMID 33089034, 2020). "Additionally, we discovered a novel subpopulation of CD14+ monocytes associating with the acute phase of infection that expressed high levels of CCR4, CXCR3, and CCR6, among other markers." (PMID 30150281, 2018). "In addition to the previously reported elevated levels of HIV receptors and decreased CCR5 ligands, these findings suggest that additional post-entry cellular factors contribute to the preferential infection of CCR6+ cells." (PMID 28509877, 2017). "Although MIP-3α inhibits HIV-1 replication in vitro, MIP-3α is strongly chemotactic for CCR6+ cells and therefore in vivo MIP-3α may contribute to the spread of infection by recruiting these highly susceptible cells to sites of infection." (PMID 28509877, 2017). "Interestingly, CCR6+CCR4+ Th17 cells are specific for Candida albicans and CCR6+CXCR3+ Th17 cells are specific for Mycobacterium tuberculosis, two HIV-1 associated infections." (PMID 28509877, 2017). "CCR6 expression also promotes the activation of Salmonella-specific T cells upon infection." (PMID 29038658, 2017). "The preferential infection and depletion of CCR6+CD4+ T cell subsets may initiate or contribute to the failure of the gut mucosal immune system." (PMID 28509877, 2017). "The preferential infection of CCR6+ Th17 cells may be attributable to the higher expression of the viral receptors CD4, CXCR4, and α4β7 compared with CCR6− Th17 cells resulting in enhanced HIV envelope binding." (PMID 28509877, 2017). "As well as expression by innate-like lymphocytes, Ccr6 is abundant on Th17 cells and we speculate that Th17 effector cells that remain in the LN following immunization or infection may position in proximity with the SCS." (PMID 27487469, 2016). "This raised the possibility that CCR6+DN are resistant to infection." (PMID 27553844, 2016). "Later on in infection, at week 10, the increase in the mRNA levels of Tbet, GATA3 and RORγC paralleled the reduction in expression levels of the Treg-associated molecules Foxp3, PD-L1, CCR5, CCR6 and Granzyme B." (PMID 26512987, 2015). "CCR6 also facilitated infection by an equal number of viruses in our previous study yielded." (PMID 24980635, 2014). "However, following infection with Trichuris, CCR6−/− mice were able to completely clear their worm burdens." (PMID 23555902, 2013). "At 70% of infections via CCR6, RT level was 2.5×105 cpm/mL there." (PMID 24009735, 2013). "Moreover, CCR6 was found to support infection for three isolates out of 18 HIV/ SIV used in the study and hence justified as a low-efficient entry co-factor than major ones." (PMID 24009735, 2013).
infection (continued). "Other potential scenarios are that this cell population is redistributed to tissues upon infection, which could explain in part the low levels of CCR6 expression on this subset in HIV and TB infected individuals." (PMID 24391773, 2013). "MPXV infection ablated CCR6 expression on all four NK cell subsets." (PMID 24147080, 2013). "Similarly, SIVsmE660 started very slow and steady infection through CCR6-coreceptor and about 2% of the cells became IFA-positive after cultivation for up to four weeks." (PMID 24009735, 2013). "Infection-induced syncytia in NP-2/CD4/CCR6 cells were detected by Giemsa staining." (PMID 24009735, 2013). "Consequently, the clearance of L. major parasites in the lymph nodes and at the site of infection was comparable between B6.CCR6−/− and B.6.WT mice." (PMID 23028548, 2012). "Whether CD8+ T-cells colocalize in excess with CCR6+CD4+ T-cells for an efficient control of HIV replication in SP subjects during the first years of infection or in HIV-exposed uninfected individuals remains to be determined." (PMID 22470433, 2012). "However, B6.CCR6−/− mice were able to resolve the infection with the same kinetics as wild type (B6.WT) mice." (PMID 23028548, 2012). "At the peak of infection B6.CCR6−/− mice developed more severe lesions than B6.WT mice." (PMID 23028548, 2012). "Many T and B cell immunotypes – Treg TEM, NSM and CSM cells – downregulated the lymph node homing molecule CCR6 over the course of disease primarily during active infection, which may impede homing to inflamed tissues and development of germinal center responses." (PMID 34867943, 2021). "In addition, a disruption of the chemoattractant axis CCL20/CCR6 in Il1a-/- mice could explain the reduced Th17 response after 30 days of infection." (PMID 31425553, 2019). "Consequently, CD4+CCR6+ cell numbers started to rise from d 6 of infection in the lymph node." (PMID 23028548, 2012). "Hence, we were questioning whether the increased inflammatory response observed in the lymph nodes might result in a more pronounced inflammation at the site of infection in CCR6-deficent mice." (PMID 23028548, 2012). "Additionally, the spontaneous development of CCR6+ Th17 cells could be shown in autoimmune prone mice but the stimulatory requirements for the development of Th17 cells in the course of an infection are yet ill-defined." (PMID 18698357, 2008). "We identified CCR6, important for HIV-1 permissiveness, to be significantly upregulated upon infection." (PMID 41857366, 2026). "CXCR3 and CCR6 were used to study the other CD4+ T-helper cell (Th) populations, in relation to the different latency profiles and infection statuses." (PMID 40963636, 2025). "These recruited T cells, already expressing Ccr6, likely respond to CCL20 gradients to migrate to the site of infection." (PMID 40127923, 2025). "Since the Itgα4β7+ CD4+ T-cell subset predominantly consists of CCR6+ Th17 cells, their capacity to migrate into the GALT justifies our findings that CCR6+Itgβ7+ CD4+ T-cells are selectively targeted by HIV-1 for infection." (PMID 41227377, 2025). "In memory CD8+ T cells, during infection, only CXCR3 presented greater expression than CCR5, while in the control group, both CXCR3 and CCR6 exhibited greater expression than CCR5." (PMID 39867906, 2024). "Group I showed greater numbers of all CCR6+ B-cell subsets and CXCR3+ naive B cells and plasma cells than did Group C. Infection of the nurslings promoted increased CCL20, CXCL10, IL-6, IL-8, total IgA, and IgG levels in the milk." (PMID 39867906, 2024). "Increased infiltration of CCR6+ lymphocytes with upregulated CCL20 expression was found in tissue microenvironment during inflammation, infection and malignant lesions in various organs, such as stomach, intestine, liver and lung." (PMID 38524129, 2024). "Two different CD4 T-cell clusters expressing high levels of CCR6+ and S100A4+ appeared late post-infection in young and aged animals, respectively." (PMID 38771046, 2024).
infection (continued). "CCl20 and its receptor, CCR6, control the migration of dendritic cells and Th17 CD4+ T cells to the site of infection and inflammation." (PMID 37243277, 2023). "The CCL20 ligand for CCR6 can facilitate nuclear integration of HIV-1 by remodelling the actin cytoskeleton, but also directly inhibits infection in the female reproductive tract." (PMID 35418589, 2022). "In contrast, following infection with JKD6159-gD, activated CD4+ T cells were predominantly IL-17 producing Th17, and of the divided cells, 40% downregulated CD62L, 26% upregulated CCR6, while only 20% upregulated CXCR3." (PMID 35637249, 2022). "CCL20 attracts CCR6+ cells such as dendritic cells (DCs) and CD4+ TH17 cells that migrate along the CCL20 gradient to the site of infection." (PMID 33659876, 2021). "Within this experimental infection model, Th2- (CXCR3− CCR6−) and Th1-cTfh (CXCR3+CCR6−) subsets were activated with different kinetics." (PMID 36845571, 2021). "We found that relatively few MAIT cells expressed CCR2, CCR4, CCR6, CXCR3, CXCR4, and CCR9 in the lungs, spleen, thymus, and LP both before and after infection." (PMID 32849637, 2020). "Most of the genes for chemokines/chemokine receptors (CCR2, CCR6, CCR7, CSF2RB, CX3CR1 and CXCR4) and cytokines/cytokines receptors (IL1R2, IL8, IL18, IL20RA and IL22RA2) were down-regulated after infection by vvIBDV at 3 dpi." (PMID 33110122, 2020). "Several sudies have shown that memory CCR6+ Th17 cells are highly permissive to SIV/HIV infections, and a rapid depletion of these cells happens rapidely following infection (5, –, 7, 11, 54)." (PMID 31315987, 2019). "Multifunctional Th17 cells (IFN-γ+IL-17A+) co-expressing CXCR3/CCR6 are known to upregulate the ligands for CXCR3 (CXCL9/CXCL10/CXCL11) on the lung parenchymal cells, which helps to recruit Th1 cells to the site of infection." (PMID 28985739, 2017). "Splenic CD4+ YFP+ GFP+ T cells from mice on day 7 of infection were almost universally CXCR3+, whereas they expressed only low levels of CCR1, CCR6, and CXCR6." (PMID 26459508, 2016). "The expression of Ccr6 was down-regulated in all analyzed mouse strains, but very strongly in CAST/EiJ lungs, especially at day 5 after infection." (PMID 26921172, 2016). "The majority of initial (d7 post inoculation) Th17 cells generated in response to infection expressed CCR6 and were followed by the later emergence of CCR6−CCR2+ Th17 cells by d21 post infection." (PMID 26511769, 2015). "CCR6 is also one of the characteristics for a specific population of memory cells that secrete TNF-α, IL-2, and IFN-γ upon infection." (PMID 25894562, 2015). "CKR-L3 is a five amino acid deletion mutant from NTR compared to CCR6 providing accelerated and better infection efficiency in the NP-2/CD4 cell system." (PMID 24980635, 2014). "The RT activities at the final time point of infection cycles were 1.7 × 105, 1.6 × 105 and 1.2 × 105 cpm/mL using CCR5, CKR-L3 and CCR6 coreceptors respectively when 80-90% cells become antigen positive by IFA." (PMID 24980635, 2014). "To study the potential of NK cells to migrate to infected peripheral tissues upon MPXV infection, we assessed the expression of chemokine receptors CXCR3, CCR5, CCR6, and CCR7 on each NK cell subset." (PMID 24147080, 2013). "As Th17 cell-mediated granulocyte recruitment and activation in the chronic phase of infection correlates with tissue damage, the recruitment of granulocytes might favor further tissue damage and promote local inflammation following L. major infection in B6.CCR6−/− mice." (PMID 23028548, 2012). "To test the role of CCR6 on Tc17 cells, we neutralized its chemokine ligand CCL20 during the effector phase (or recall response) after infection." (PMID 22829762, 2012). "Accordingly, CCR6−/− mice exhibit impaired Th cell function in delayed type of hypersensitivity reactions (DTH) and in re-infection experiments." (PMID 18698357, 2008).
infection (continued). "In our efforts to uncover its role, we reveal that osteoblasts and macrophages secrete CCL20 in response to infection, and mice lacking CCL20 or its monogamous receptor CCR6 are more susceptible to S." (PMID 40853122, 2025). "Intriguingly, while the proportion of IL-17-producing CCR6+ CD4+ T cells or TEMRA CD8+ T cells did not change by 28 days after infection, the proportion of IFN-γ-producing TEMRA CD8+ T cells declined by 28 days (P < .01)." (PMID 39008280, 2024). "As expected from the short interval spanning between infection and sample collection, the maternal frequency of B cells, class-switched IgD– B cells, CD4+ T cells, activated CD4+ T cells, CCR6+ T cells, and CXCR5+ T cells remained equivalent in the presence or absence of symptoms." (PMID 37490342, 2023). "Although IEC stimulation increased HIV infection rates in both CCR6 − and CCR6 + T cells (comparisons between IEC stimulated T cells versus T cells alone, p < 0.0001), in CCR6 + T cells there was a greater increase in infection rates than in CCR6- T cells." (PMID 37202790, 2023). "Levels of CCR6 + cells were compared between infected and uninfected total CD4 + T cells on day 6 post infection, whether cultured alone or in IEC co-cultures." (PMID 37202790, 2023). "There was no drop of CCR6 + T cells in IEC co-culture without infection, suggesting the drop was not due to IEC stimulation of CD4 + T cells only." (PMID 37202790, 2023). "The frequencies of Th17 (CCR6+CXCR3-) cells were significantly increased in patients already on day 2 compared to the healthy controls and Th17 responses remained significantly elevated until day 7 of infection." (PMID 37809062, 2023). "Th17 cell expression of mucosal migration receptors (CCR6 and α4β7), as well as HIV co-receptors (CD4, α4β7, CCR5, and CXCR4), participates in the remarkable capacity of these cells to disseminate HIV following initial infection." (PMID 35197986, 2022). "Strong inflammatory immune responses induced in ICU-admitted SARS-CoV-2-infected patients were characterized by high IL-6 and IL-17 levels, CCR6+ circulating (c)TFH17 cells in the blood, and anti-S IgG1 Abs with very low galactosylation levels that prevailed upon day 50 post-infection." (PMID 36713457, 2022). "Infection with HSV-1 resulted in the generation of predominately IFNγ producing Th1 cells, and assessment of the divided cells (CFSElo) revealed that 78% downregulated CD62L, 5% upregulated CCR6, while 70% upregulated CXCR3." (PMID 35637249, 2022). "Thus, it is conceivable that atypical MBCs expressing high levels of CCR6 found in individuals carrying P. vivax infection might constitute a population of low-affinity MBCs with poor effector capacity rapidly emerging from GC reactions in response to infection." (PMID 34128836, 2021). "The preferential infection of Th17 cells in vivo is consistent with cells expressing the Th17 marker CCR6 harboring more HIV DNA than those lacking expression of this marker in individuals with viremia." (PMID 33910003, 2021). "Furthermore, we demonstrated that specific ligands for both CCR6 and CXCR3 (MIP‐3α and CXCL9/10, respectively) were expressed in the trachea after infection, suggesting their involvement in the recruitment of γδ T cells." (PMID 31777067, 2020). "Evaluation of infection-induced changes in CD4 T cell differentiation at Day 7 revealed a strong phenotypic shift to Th1 effectors (CXCR3+), Th1 polarized Tfh cells (CXCR3 + CXCR5+) and Th1 Th17 (CXCR3 + CCR6+) CD4 T cells." (PMID 32818217, 2020). "Although our data showed that CXCR6 was not essential for MAIT cell recruitment during LVS infection, this does not rule out a non-redundant role for the CCR6/CXCL16 axis in MAIT cell accumulation." (PMID 32849637, 2020). "In rectal tissue, the high proportion of CCR6+CXCR3+ T cells coexpressing the CCR5 HIV coreceptor may allow preferential productive infection of this subset." (PMID 31796951, 2020).